GLS (glutaminase)
Diseases named in the same sentence as GLS in open-access papers (continued):
Sharing a sentence is not in itself a finding about the gene and the disease.
leukemia (28 papers, 2015 to 2024). A malignant (clonal) hematologic disorder, involving hematopoietic stem cells and characterized by the presence of primitive or atypical myeloid or lymphoid cells in the bone marrow and the blood. "Our previous study investigated the cause of leukemia cells apoptosis induced by plasma with metabonomics level, and it was inferred that plasma leads to a reduction in glutaminase activity in leukemia cells, thereby inhibiting glutamine metabolism." (PMID 33816218, 2021). "In vivo studies demonstrated that glutaminase-deficient L-ASNase was insufficiently active to prevent the recurrence of leukemia." (PMID 34948436, 2021). "Glutaminase C has higher catalytic activity than kidney glutaminase and is commonly upregulated in leukemia cells." (PMID 37228498, 2023). "It is proved that GLS inhibitors can exert synergistic anti-leukemia effects with adjuvant drugs that disturb mitochondrial redox status, such as arsenic trioxide (ATO) and homeopathic erythromycin (HHT)." (PMID 37249801, 2023). "ASNase, which mainly catalyzes the hydrolysis of asparagine, also exhibits glutaminase activity that generates glutamate from glutamine, which is not required for its anti-cancer capability and even induces cytotoxicity in leukemia cells." (PMID 35178349, 2022). "The long-term evaluation found that leukemia progression was significantly delayed in mice treated with either IACS-01075 or subjected to GLS knockout (p = 0.0001)." (PMID 35589701, 2022). "Taken together, our results demonstrate that blocking GLS in combination with complex I inhibition provides a powerful approach to abrogate leukemia progression in vivo." (PMID 35589701, 2022). "Glutaminase inhibition can promote leukemia cells to overcome drug resistance, and to be sensitive to BCL2 inhibitors, FMS-like tyrosine kinase 3 and other tyrosine kinase inhibitors." (PMID 36618700, 2022). "Our previous studies have shown that glutaminase activity in leukemia cells was inhibited after plasma treatment." (PMID 33816218, 2021). "We also inhibited GLS activity of leukemia cells by BPTES and found that inhibiton of GLS activity reduced cell viability." (PMID 31130824, 2019). "In order to determine its reason, we investigated that GLS activity in leukemia cells after plasma treatment, and the result showed that GLS activity was decreased." (PMID 31130824, 2019). "The mutant shows completely preserved asparaginase and glutaminase activities, long-term storage stability, improved thermal parameters, and outstanding resistance to proteases derived from leukaemia cells." (PMID 29101342, 2017). "Strategies of targeting glutaminase (which generates glutamate from glutamine) or glutaminolysis pathway proteins are developed to suppress tumor growth in leukemia, liver and pancreatic cancers, all of which showed therapeutical efficacy at least in preclinical studies." (PMID 35178349, 2022). "Taken together, our data indicate that OxPhos-i combined with standard-of-care chemotherapy containing l-asparaginase, with its GLS-inhibitory activity, effectively induces metabolic and transcriptomic cellular catastrophe that impedes leukemia progression and leads to the extension of survival." (PMID 35589701, 2022). "Our previous studies also demonstrated that leukemia cells viability could decrease when glutaminase activity was inhibited." (PMID 33816218, 2021). "We found that when glutaminase was inhibited, leukemia cells activity was decreased." (PMID 31130824, 2019). "However, when added glutamate to leukemia cells inhibited GLS activity, we found increased relative cell activity." (PMID 31130824, 2019). "Glutaminase activity was decreased after plasma treatment, which might lead to glutamine accumulation and leukemia cells death." (PMID 31130824, 2019).
leukemia (continued). "To determine whether the differentially metabolic pathway and the differential metabolite were responsible for leukemia cells death, we analyzed glutaminase activity of leukemia cells before and after plasma treatment." (PMID 31130824, 2019). "Inhibition of glutaminase can inhibit leukemia cell growth and even induce apoptosis." (PMID 31130824, 2019). "Drugs targeting GLS activity such as BPTES (bis-2-(5-phenylacetamido-1,2,4-thiadiazol-2-yl)ethyl sulfide 3) or CB-839 have gained attention owing to their potent inhibition of GLS1 activity and anti-proliferative effect in multiple tumor subtypes including leukemia and triple negative breast cancer." (PMID 29212209, 2017). "However, recent study showed that asparaginase exhibited significant cytotoxicity of ASNS-positive cancer cells including K562, SR leukemia cells, and this anticancer activity might due to the glutaminase activity of asparaginase." (PMID 25738356, 2015). "First, glutaminase is upregulated expression in AML, and glutamine metabolism is important for the maintenance, relapse, and refractory of leukemia." (PMID 36618700, 2022). "We first postulated a completely different role for GLS and GLS2 isoforms in cancer based on their relative expression patterns in human leukemia, breast cancer cells, and hepatocellular transformation." (PMID 32042057, 2020). "Since the clinical toxicity of L-ASP is thought to derive from its glutaminase activity, these findings suggest the hypothesis that glutaminase-negative variants of L-ASP could exert a stronger therapeutic activity than wild-type L-ASP for ASNS-negative leukemias." (PMID 30813354, 2019). "Following established leukemia engraftment in peripheral blood at day 7, mice received vehicle or IACS-010759 therapy, alone or with concomitant tamoxifen administration to induce GLS knockout selectively in leukemic cells." (PMID 35589701, 2022). "When used in combination with drugs that increase ROS formation, like arsenic trioxide or homoharringtonine, inhibitors of glutaminase (GLS), the first enzyme in glutaminolysis, significantly decreased the viability of AML cells and leukemia burden in treated mice." (PMID 34094959, 2021). "However, more recent results from the same group, obtained with a murine leukemia model of ASNS-null ALL, indicate that, actually, glutaminase activity was needed for a durable suppression of the tumor." (PMID 31998641, 2019). "We analyzed expression of the full-length GLS protein KGA (669 aa) and the shorter isoform GAC (598 aa) in a panel of leukemia cell lines (n = 10) and in 3 primary AML samples using GAC (Proteintech 19958-1-AP 1:1000) and KGA-GAC (Abcm 156876) specific antibodies." (PMID 27806325, 2016). "Several selective inhibitors of glutaminase (GLS), the rate-limiting enzyme responsible for the deamination of glutamine to glutamate, such as BPTES or CB-839, have now been tested in several pre-clinical cancer models including NSCLC, breast, pancreatic, renal, leukemia and lymphoma." (PMID 32718002, 2020). "We therefore hypothesized that glutaminase activity of plasma-treated leukemia cells was reduced and glutamine could not be normally metabolized and converted to glutamic acid, which suppressed the proliferation of leukemia cells and even leaded to leukemia cells apoptosis." (PMID 31130824, 2019). "Thus, concomitant administration of GSI and glutaminase (GLS) inhibitors showed synergistic anti-leukemic effects against Pten-positive T-ALLs, while Pten-negative leukemias were resistant not only to GSI but also to the combination of both GSI and GLS inhibitors." (PMID 36674902, 2023).
triple-negative breast carcinoma (27 papers, 2016 to 2026). An invasive breast carcinoma which is negative for expression of estrogen receptor (ER), progesterone receptor (PR), and human epidermal growth factor receptor 2 (HER2). "Using inducible shRNA mediated gene knockdown, we discovered that loss of GLS function in triple-negative breast cancer (TNBC) cell lines with a deregulated glutaminolysis pathway led to profound tumor growth inhibition in vitro and in vivo." (PMID 28950000, 2017). "Furthermore, our work reveals a novel function for the c-Jun oncoprotein in cancer, and suggests why certain types of cancer such as triple-negative breast cancer might be more susceptible to glutaminase-targeted therapy." (PMID 27089238, 2016). "Many tumors are reliant on glutamine as a critical carbon and nitrogen source, with glutaminase inhibition shown to be an effective therapy in several cancer types, such as triple-negative breast cancer, non-small cell lung cancer, and head and neck cancer." (PMID 40473840, 2025). "Glutaminase (GLS), which generates glutamate from glutamine, plays a role in triple-negative breast cancer (TNBC)." (PMID 38893070, 2024). "CB839, a small molecule inhibitor of glutaminase, is garnering attention due to its potential efficacy in glutamate ‘addicts’ like triple negative breast cancer and renal cell carcinoma." (PMID 37887398, 2023). "Glutaminase inhibitors have shown efficacy in preclinical cancer models for triple-negative breast cancer, acute myeloid leukemia, and renal cell carcinoma." (PMID 36650542, 2023). "Increased glutaminase has already been demonstrated in glioma, non-small cell lung cancer, pancreatic cancer and triple-negative breast cancer cells, among others." (PMID 34572047, 2021). "CB-839 is a potent, selective, orally bioavailable inhibitor of glutaminase that has activity in Triple receptor-Negative Breast Cancer (TNBC) cell lines and evidence of efficacy in advanced TNBC patients." (PMID 32450839, 2020). "Clinical trials with GLS inhibitor CB839 have already given some promising results in triple-negative breast cancer and renal cell carcinoma." (PMID 32789014, 2020). "Previous studies suggest that basal-like and triple-negative breast cancers are more sensitive to glutaminase inhibitors than luminal-like and ER+ subgroups." (PMID 31088535, 2019). "We tested CB-839, a glutaminase inhibitor shown to mimic glutamine withdrawal in triple negative breast cancer cells." (PMID 30176945, 2018). "In triple-negative breast cancer, the glutaminase inhibitor CB-839 is effective both as a single agent and in combination with paclitaxel, and has entered clinical trials." (PMID 28759021, 2017). "A selective glutaminase inhibitor, CB-839, which targets cancer cells by blocking glutamine conversion to glutamate, has shown promising preclinical results as a therapeutic target in triple-negative breast cancer treatment." (PMID 41898641, 2026). "The effect of glutaminase inhibitor CB-839 could be demonstrated in triple-negative breast cancer cells." (PMID 34572047, 2021). "The library was further tested in four bioassays: proteasome inhibition, triple-negative breast cancer cell-based assay targeted for glutaminase inhibition, and Gram-positive and Gram-negative bacterial growth inhibition." (PMID 33673148, 2021). "The entire EPfB chemical library was further tested in four biological assays, being three cell-based assays—triple-negative breast cancer cells targeted for glutaminase inhibitors and Gram-positive/Gram-negative bacteria—and one enzymatic assay—proteasome inhibition (ChTL subunit)." (PMID 33673148, 2021). "The CMR inhibitor CB-839 is a reversible non-competitive allosteric glutaminase (GLS) inhibitor, exhibiting anti-proliferative activity in triple-negative breast cancer cell lines, and in xenografts." (PMID 33005401, 2020).
non-small cell lung carcinoma (24 papers, 2014 to 2025). A group of at least three distinct histological types of lung cancer, including non-small cell squamous cell carcinoma, adenocarcinoma, and large cell carcinoma. "Additionally, higher mRNA expression of GLS has been detected in KRAS-mutated non-small cell lung cancer (NSCLC)." (PMID 38459595, 2024). "Emerging trials combining PI3K/mTOR inhibitors or glutaminase blockers (CB-839) with conventional chemotherapy in KEAP1-mutant non-small-cell lung cancer exemplify how mechanistic insights are being translated into clinical strategies." (PMID 41470226, 2025). "Glutaminase inhibitor CB-839 is currently being evaluated in the clinic for a combination treatment approach in non-small cell lung cancer patients." (PMID 38769385, 2024). "The expression and activity of GAC, a major form of glutaminase in tumors, is upregulated in multiple cancers and contributes to tumorigenesis including in non-small cell lung cancer 10-13." (PMID 35864951, 2022). "Non-small-cell lung cancer (NSCLC) cell lines vary in their sensitivity to glutaminase inhibitors, so it is important to identify the metabolic assets underling their efficacy in cancer cells." (PMID 32718002, 2020). "Herein we validate a small molecule inhibitor of GLS and show that non-small cell lung cancer cells marked by low E-cadherin and high vimentin expression, hallmarks of a mesenchymal phenotype, are particularly sensitive to inhibition of the enzyme." (PMID 25502225, 2014). "We first detected the expression pattern of glutaminase in non-small cell lung cancer cells." (PMID 28039459, 2017). "Glutaminase 1 (GLS1) expression is increased in non-small cell lung cancer (NSCLC)." (PMID 27929535, 2016). "Other GLS inhibitors, such as IACS-6274 in head and neck squamous cell carcinoma (HNSCC) and IPN60090 in non-small cell lung cancer (NSCLC) and ovarian cancer, have demonstrated efficacy in preclinical models." (PMID 41041303, 2025). "CB-839, a potent reversible noncompetitive allosteric GLS inhibitor, in combination with erlotinib for EGFR-mutated non-small cell lung cancer, inhibits tumor growth by impairing both glucose and Gln utilization." (PMID 35223460, 2021). "Concerning the targeting of glutamine metabolism, there is one ongoing clinical trial testing the inhibition of glutaminase (GLS), the first enzyme involved in glutaminolysis, in combination with chemotherapy plus anti-PD1 for the treatment of non-small cell lung cancer." (PMID 33177494, 2020).
liver cancer (19 papers, 2015 to 2025). An epithelial or non-epithelial malignant neoplasm that arises from the liver. "In liver cancer, GCN5L1 acetylates glutaminase, inhibiting its activity and the mTORC1 pathway, thereby controlling the development of liver cancer." (PMID 39778006, 2025). "Glutaminase 1 (GLS1) facilitates the conversion of glutamine to glutamate, and co-treatment with the GLS1 inhibitor CB-839 and the glutamine transporter inhibitor V-9302 induced apoptosis in mouse liver cancer cells and suppressed HCC xenografts." (PMID 39610917, 2024). "In a recent study, it was found that posttranslational modifications of PDHC and GLS are involved in liver cancer metabolism and biogenesis." (PMID 37124062, 2023). "GLS, as a mitochondrial glutaminase, which hydrolyzes glutamine to glutamate, has a close relationship with liver cancer progression." (PMID 36033443, 2022). "The HGF-MET axis was reported to inhibit pyruvate dehydrogenase complex (PDHC) activity but activate GLS to facilitate glutaminolysis in multiple liver cancer cells." (PMID 33016874, 2020). "Additionally, SIRT2 increases the activity of Phosphoenolpyruvate Carboxykinase 1 (PEPCK1) and Glutaminase (GLS), which promote the metabolism of glycolysis and inhibit the E-cadherin pathway, which promotes the invasion of liver cancer cells." (PMID 36750593, 2023). "Moreover, GLS inhibition with BPTES prolonged the survival of a MYC-overexpressing mouse model of liver cancer, with MYC-dependent GLS expression." (PMID 34588983, 2021). "However, targeting glutamine addiction using the glutaminase inhibitor CB-839 as monotherapy had a very limited anticancer effect, even against the most glutamine addicted human liver cancer cells." (PMID 33016874, 2020). "Knocking down of PTBP1 significantly blocked the protein expression of GLS, which catalyzes the speed-limiting reaction of glutamine metabolism in HCC cells and was significantly upregulated in liver cancer (Figure A4)." (PMID 37724122, 2023). "MYC increases catabolism of glucose and glutamine in liver cancer, while MYC-driven lung tumors show increased expression of glutamine synthetase and glutaminase." (PMID 33652667, 2021). "Our findings indicate that dual inhibition of glutamine metabolism by targeting both glutaminase and glutamine transporter ASCT2 represents a potential novel treatment strategy for glutamine addicted liver cancers." (PMID 33016874, 2020).
gastric cancer (16 papers, 2019 to 2026). A primary or metastatic malignant neoplasm involving the stomach. "This process upregulates GLS expression and promotes the proliferation, migration, and Gln metabolism of gastric cancer (GC) cells." (PMID 40276500, 2025). "NSUN2 methylates lncRNA NR‐033928, stabilizing glutaminase (GLS) mRNA and promoting glutamine metabolism reprogramming, which increases gastric cancer proliferation." (PMID 39802639, 2025). "SEM-type gastric carcinomas exhibit marked resistance to chemotherapy, and it was found that these carcinomas highly express the glutaminase GLS, but they are resistant to glutamine catabolism inhibition." (PMID 40018041, 2025). "Consistently, we found that GATA6 knockout resulted in decreased expression of GLS and thereupon disturbed glutamate and glutamine metabolism in trastuzumab resistant gastric cancer cells." (PMID 33173435, 2020). "GLS mutations mainly occurred in uterine, lung, and stomach cancer, whereas GLS2 mutations were mainly found in uterine, lung, and stomach cancer." (PMID 30871151, 2019). "NR_033928, in turn, interacts with the IGF2BP3/HUR complex to upregulate the expression of glutaminase (GLS), thereby increasing the stability of GLS mRNA and promoting the progression of gastric cancer." (PMID 40370440, 2025). "Copper death related genes such as LIAS, GLS, and CDKN2A can regulate the function of immune cells, affect the occurrence and development of gastric cancer, and serve as biomarkers for gastric cancer patients." (PMID 41158129, 2025). "NSUN2 methylates lncRNA NR_033928, interacts with the IGF2BP3/HUR complex to upregulate the expression of glutaminase (GLS), promoting the stability of GLS mRNA and advancing gastric cancer." (PMID 38543171, 2024). "This study suggests that targeting both the GLS pathway and the PHGDH pathway may represent a promising therapeutic strategy for patients with chemotherapy‐resistant gastric cancer, as validated in patient‐derived organoids." (PMID 40365984, 2025). "Additionally, NSUN2-methylated lncRNA enhances the stability of glutaminase (GLS) mRNA by upregulating glutaminase expression through interaction with the IGF2BP3/HUR complex, thus facilitating reprogramming of glutamine metabolism and accelerating gastric cancer progression." (PMID 38902779, 2024).